CD4 (CD4 molecule)
Diseases named in the same sentence as CD4 in open-access papers (continued):
Sharing a sentence is not in itself a finding about the gene and the disease.
Sepsis (continued). "Thirty-five HIV-infected patients undergoing abdominal operations with pre-operative CD4 <200 or CD4/CD8 ratio <0.15 had overall higher post-operative sepsis morbidity." (PMID 27747712, 2016). "From 12 to 72 hrs, compared with the control and sham groups, the expression of Nrp-1 on CD4+CD25+Tregs was significantly enhanced by sepsis (P<0.01)." (PMID 27835904, 2016). "In the current study, we first reported that sepsis per se markedly promoted the expression of Nrp-1 on CD4+CD25+Tregs in a grade- and time- dependent manner." (PMID 27835904, 2016). "With the development of sepsis, Tregs can mainly inhibit the activation of T lymphocytes, especially CD4+T lymphocytes through various suppressive mechanisms." (PMID 27835904, 2016). "In CD4+ cells of sepsis survivors, the receptor density of PD-1 appeared to be downregulated, but was upregulated for BTLA." (PMID 27056672, 2016). "Recently, we demonstrated that tuftsin-derived T-peptide had potential effect on adaptive immunity in sepsis, such as lowering the suppressive ability of CD4+CD25+ Tregs on CD4+CD25− T cells." (PMID 27835904, 2016). "In HIV-infected patients, CD4 count and albumin levels negatively correlate with incidence of post-operative sepsis, whereas surgical infections and previous major surgical procedures positively correlated with the incidence of post-operative sepsis." (PMID 27747712, 2016). "At first, large amounts of studies on animals or patients had featured obvious loss of CD4+ and CD8+ T cells in sepsis." (PMID 25821827, 2015). "Treg are more resistant to sepsis-induced apoptosis than are other effector CD4 T cells, which explains the increased percentage of circulating Treg in patients with sepsis." (PMID 26693207, 2015). "It has been known that immune dysfunction of CD4+ T lymphocytes is one of the primary cellular mechanisms in sepsis-induced immunosuppressive state." (PMID 26577833, 2015). "Our results showed that the percentage of BTLA+/CD4+ T cells was high expression in healthy volunteers and it was statistically reduced in severe sepsis and septic shock compared with healthy controls(all P<0.01)." (PMID 26329820, 2015). "Sepsis-induced abnormalities of CD4 T-cell subpopulations were reported, including polarization to the Th2 subset and increments of Treg populations." (PMID 26693207, 2015). "CD4+ T cells, including T helper (Th) cells and regulatory T cells (Treg), play important roles in immune homeostasis during sepsis." (PMID 26693207, 2015). "We explore BTLA expression on CD4+ T cells in healthy controls and septic patients, and assess the correlation of BTLA expression on CD4+ T cells in the early stage of sepsis with the severity and mortality of septic patients in the emergency department (ED)." (PMID 26329820, 2015). "Shubin and colleagues also measured the percentage of BTLA+/CD4+T cells in patients with SIRS or sepsis." (PMID 26329820, 2015). "The percentages of BTLA+/CD4+T cells were significantly reduced in patients with severe sepsis or septic shock compared with healthy controls." (PMID 26329820, 2015). "We conducted an initial study of adaptive immunity during sepsis progression by incorporating CD4+ T cells, CD8+ T cells, B cells, and antibodies to the SDMM." (PMID 26446682, 2015). "In this study, ouabain reversed not only the impairment in TNF-α production in monocytes, but also the sepsis-induced reduction in CD4+/CD8+ T cells." (PMID 25535255, 2015). "Our findings suggest that not only did the percentage of BTLA+/CD4+T cells correlate with the severity of sepsis, but also it was valuable for prognostic evaluation of sepsis." (PMID 26329820, 2015). "Other useful tests would have been CD4 counts and HIV viral load counts for all the patients to assess the impact of HIV on severity of AKI in sepsis and the possible development of HIV associated nephropathy." (PMID 25592556, 2015).
Sepsis (continued). "We also examined the correlation between the level of BTLA expression on circulating CD4+ T lymphocytes and the disease severity and mortality of patients with sepsis." (PMID 26329820, 2015). "Both the initiation and progression of sepsis seems to be orchestrated by activated T cells, particularly CD4+ T helper 1 (Th1) and Th2 cells." (PMID 26111529, 2015). "Previous studies showed that sepsis results in significant decrements in T lymphocytes and CD4 cell numbers and impairment of T-cell functions." (PMID 26693207, 2015). "Blood lymphocyte dysfunction during sepsis has long been recognized with significant lymphopenia and decreased lymphocyte T CD4+, CD8+, and natural killer (NK) cells." (PMID 25302303, 2014). "Upon activation using an anti-CD3/28 antibody, CD25 expression in CD4+ T cells was lower in adult and elderly patients than in HDs, which suggests that immunosuppression occurred even in the relatively early phase of sepsis." (PMID 24962182, 2014). "The associations between complicated clinical course and unfavorable prognosis of septic patients with the decline of peripheral blood CD4+ T-lymphocytes were established in a majority of trauma victims or surgical patients with secondary sepsis." (PMID 25302303, 2014). "In the present study we demonstrated that mice with disruption of Atg7 in T cells exhibited a reduced cytokine production of IL-2, IFN-γ, IL-4, IL-10 and IL-17 by CD4+ T cells after sepsis, compared to septic wild-type mice." (PMID 25029098, 2014). "For example, CD4+/CD8+ lymphocytes collected from patients deceased during acute sepsis feature reduced cytokine production and activation marker expression in response to soluble CD3/CD28 mAb mediated TCR/co-receptor stimulation." (PMID 25541945, 2014). "To understand if these alterations reflected a defect inherent to T-cells, we went on to investigate T-cell activation in vitro using isolated, highly pure native polyclonal CD4+/CD8+ lymphocyte preparations isolated 10 d post SIRS/sepsis." (PMID 25541945, 2014). "This was accompanied by suppressed Th1/Th2/Th17 cytokine production by CD4+ T cells, reduced phagocytic activity in macrophages, and decreased bacterial clearance in the spleen in sepsis." (PMID 25029098, 2014). "Recently, ATP content of CD4+ T cells (ATP_CD4) has been shown to correlate with survival in sepsis." (PMID 25522739, 2014). "Differences in the impact of the various SIRS/sepsis models on the adaptive immune system are illustrated also by the distinct vulnerability of CD4+ versus CD8+ T-cells to any particular insult." (PMID 25541945, 2014). "Among the HIV patients, sepsis was confirmed in 37.5% (n = 3) of the 8 patients with a CD4 count <100 cells/μL and in 20% (n = 1) in the 5 patients with a CD4 count ≥100 cells/μL (P value = 0.49)." (PMID 24895569, 2014). "A highly similar effect of anti-PD-1 and anti-PD-L1 antibody on sepsis-induced apoptosis was observed in CD4 and CD8 T cells from septic patients." (PMID 24387680, 2014). "Similar to the results observed in human cells, both aging and sepsis induced a reduction of CD25 expression in mouse CD4+ T cells upon ex vivo stimulation by an anti-CD3 antibody (P <0.05)." (PMID 24962182, 2014). "Recently, postmortem studies of patients who died of sepsis have provided important insights into why septic patients die and showed an extensive depletion of CD4 and CD8 lymphocytes and they found that circulating blood cells showed similar findings." (PMID 25302303, 2014). "This was accompanied by suppressed cytokine production of Th1/Th2/Th17 by CD4+ T cells, reduced phagocytosis in macrophages and decreased bacterial clearance in the spleen after sepsis." (PMID 25029098, 2014). "Previous studies evidenced a similar high sensitivity of rodent CD4+ T-cells to endotoxemia and peritonitis-borne sepsis." (PMID 25541945, 2014).
Sepsis (continued). "In the ex vivo stimulation study, the percentage of CD25+ activated CD4+ T cells and the IL-2 concentration in the supernatants also significantly decreased in elderly patients with sepsis compared with adult patients with sepsis (P <0.05)." (PMID 24962182, 2014). "Previous work in a mouse model of septicemia showed that naïve splenic CD4 T cells have a dampened response to IL-6 compared to uninfected mice, indicated by a reduced ability to phosphorylate STAT1 in response to ex vivo IL-6 stimulation." (PMID 23754944, 2013). "The peak CRP level 70 mg/L ± 63 as a measure of acute phase response and inflammation showed a moderate but significant correlation with percentage CEACAM1 positive CD4+ T-cells in sepsis patients (R=0.553, P =0.031)." (PMID 23894299, 2013). "We are the first to demonstrate an increase in CEACAM1 positive CD4+ T-cells in peripheral blood in vivo in humans in sepsis." (PMID 23894299, 2013). "The percentage CEACAM1 positive CD4+ T-cells in the late-onset sepsis group were higher than in the VLBW infant control group (26.8% ± 24.0 versus 12.0% ± 13.0; P=0.046)." (PMID 23894299, 2013). "However, low CD4 counts may be also associated with the severity of sepsis." (PMID 23374857, 2013). "Decreased CD4+/CD8+ ratio was related to the development of severe sepsis and multiple organ failure (MOF) in trauma patients." (PMID 23327199, 2013). "In contrast, sepsis induces a marked decrease in CD4+ and CD8+ lymphocytes secondary to massive apoptosis in these cell types." (PMID 23717394, 2013). "Splenic CD4+ T cells and B cells are apoptotically lost in the lymphoid organs of critically ill patients during sepsis." (PMID 24289156, 2013). "Twenty-four hours after sepsis induction, the percentage of CD4+Foxp3+ splenocytes was significantly increased." (PMID 23724126, 2013). "As with the human subject observational study above, we evaluated changes in the level of BTLA expression on CD4+ T cells, as well as B cells, following experimental sepsis induction in mice (CLP) as compared with a sham procedure." (PMID 24289156, 2013). "HIV targets primarily CD4-positive T-lymphocytes and lymphocyte depletion is a feature of all sepsis." (PMID 23383015, 2013). "Recent data support an important role of costimulatory molecules in the regulation of inflammation in severe sepsis, and demonstrate an increase in the percentage CD4+ T-cells expressing the immune inhibitory receptor cytotoxic T lymphocyte antigen-4 (CTLA-4)." (PMID 23894299, 2013). "We employed DEREG mice (DEpletion of REGulatory T cells) and a caecal ligation and puncture model to elucidate the role of CD4+Foxp3+ Tregs in sepsis." (PMID 23724126, 2013). "Patients with lower preoperative CD4 counts undergoing surgery were more likely to develop sepsis.Surgical procedures were classified as clean (N = 82; 30.8%), contaminated (N = 171; 64.3%) and dirty (N = 13; 4.9%)." (PMID 23181440, 2012). "We found that preoperative CD4 lymphocytes, WBC and hemoglobin are independent risk factors for sepsis." (PMID 23181440, 2012). "Univariate analysis revealed that the following variables were associated with the occurrence of sepsis: preoperative WBC, hemoglobin, CD4, CD8 and CD4/CD8." (PMID 23181440, 2012). "According to our statistical analysis of the clinical data, the lower the preoperative CD4 counts, the higher the incidence of sepsis." (PMID 23181440, 2012). "CD4 lymphocyte count and admission diagnosis of sepsis are two independent predictors of hospital mortality in multivariable analysis." (PMID 21871086, 2011). "In particular, CD4+ T lymphocytes can exhibit reduced proliferative capacity and improper cytokine responses following sepsis." (PMID 21655295, 2011). "Cell surface expression of the IL-2 receptor in T cells CD4+CD25+was similar in sepsis and control samples." (PMID 21711552, 2011). "Further investigation is warranted to define the signaling transduction of APS on CD4+CD25+Treg activity in postburn sepsis." (PMID 21698274, 2011).
Sepsis (continued). "In this system, splenic CD4+ T cells from mice subjected to sham surgery (control) or CLP (sepsis) are transferred into Rag2−/− recipients, which are subsequently sensitized and challenged with model antigens in a bead model of granulomatous lung inflammation." (PMID 21655295, 2011). "Five of the 9 patients who died had CD4 counts less than 50 cells/μL, and these 5 died with clinical signs and symptoms suggestive of sepsis." (PMID 21197091, 2011). "In this study, we identified two independent predictors of hospital mortality in multivariable analysis: CD4 lymphocyte count and admission diagnosis of sepsis." (PMID 21871086, 2011). "Some authors suggest that although CD4+CD25+ Tregs induced by IL-10 seem to contribute to sepsis-induced suppression of lymphoid dependent immunity, the removal of CD25+ cells does not provide a survival advantage or disadvantage." (PMID 20064232, 2010). "CD4-lymphocyte counts have also been described to be lower among patients with sepsis due to VAP than among patients with sepsis due to other types of infection." (PMID 20504311, 2010). "We have demonstrated that there is a wide range of CD4+ lymphocyte ATP content in a typical ICU population suffering from sepsis." (PMID 20540723, 2010). "Several studies of experimental sepsis in mice have shown that CD4-lymphocytes play a pivotal role in the attempt to withhold infection spread and to format an abscess." (PMID 20504311, 2010). "• Sepsis due to VAP is characterized by decrease of CD3/CD4(+) lymphocytes and immunoparalysis of monocytes compared with sepsis caused by other nosocomial infections." (PMID 19883512, 2009). "Decrease of CD4-lymphocytes and immunoparalysis of monocytes are characteristic alterations of sepsis arising in the field of VAP." (PMID 19883512, 2009). "In patients with severe sepsis, the subpopulation with active caspase-3 was elevated in CD4+ T-cells and CD8+ T-cells compared with critically ill patients or healthy controls." (PMID 18925930, 2008). "In CD4+ T-cells (p < 0.05) and B-cells (p < 0.001) the Bcl-2 protein was decreased in severe sepsis." (PMID 18925930, 2008). "A prospective investigation in adult patients compared spleens obtained either intraoperatively or within 6 hours after death from sepsis or trauma and found that those from sepsis patients showed a marked decrease in B cells and CD4 T cells." (PMID 17479879, 2007). "CD3/CD4 cells were significantly lower in early severe sepsis patients compared with controls (P < 0.0001)." (PMID 17129388, 2006). "The presence of CD3/CD4 cells was significantly lower (P < 0.0001) and that of NK cells significantly higher among patients with sepsis compared with controls (P = 0.011)." (PMID 17129388, 2006). "As our previous work proved, deletion of mTOR decreased ERS-apoptosis of CD4 + T cells in sepsis." (PMID 41653334, 2026). "The apoptosis of CD4 + T cells may contribute to sepsis-induced immunosuppression, and preventing the induction of endoplasmic reticulum stress (ERS) can ameliorate apoptosis of CD4 + T cells in sepsis." (PMID 41653334, 2026). "Based on our observations, we propose that a possible mechanism of immune dysregulation in early pediatric sepsis involves a primary failure of the CD4 T cell regulatory response leading to an increased CD8 effector T cell response, altering the monocyte response." (PMID 39935482, 2025). "During infection, HMGB1 may serve as a putative ligand for Tim-3 on CD4+ T cells and inhibit the NF-κB signaling pathway in Tim-3+CD4+ T cells during sepsis-induced immunosuppression." (PMID 39781467, 2025). "Consequently, we have reported a population of CD69 expressing naïve CD4+ T cells for the first time in sepsis, which advances our understanding of sepsis pathophysiology." (PMID 41208955, 2025). "Taken together, our results suggest that sepsis may promote a state of immune exhaustion or tolerance in CD4+ T cells, helping to suppress the autoimmune attack on pancreatic β-cells." (PMID 41142792, 2025).
Sepsis (continued). "scRNA‐seq of sepsis revealed major immune cell changes and a distinct cDC subcluster with maturation, migration and immunoregulatory signatures, consistent with mregDCs; this sepsis‐induced mregDC subset was validated and shown to activate naïve CD4+ T cells while promoting Tregs differentiation." (PMID 41292193, 2025). "The proportion of apoptotic CD4+ T cells was significantly elevated in sepsis patients." (PMID 41306770, 2025). "In a CLP model of sepsis induction, electron microscopy revealed a reduction in autophagic vesicles within the spleens of T-cell-specific Atg7-deficient mice post-CLP, which presented increased mortality rates due to sepsis, increased T-cell apoptosis, and depletion of CD4+ and CD8+ T cells." (PMID 40153575, 2025). "After activation with anti-CD3/CD28 antibodies, flow cytometry analysis showed that CD4+ T cells from sepsis patients produced significantly less interleukin-2 (IL-2) and interferon (IFN-γ), suggesting that these cells are functionally suppressed and exhausted." (PMID 41306770, 2025). "Thus, pre-exposure of mice to sepsis led to the change of phenotypic/functional properties of CD4+ T cells, and Treg in particular, in the spleen." (PMID 41142792, 2025). "Sepsis was associated with increased infiltration of naive CD4 T cells, M0 and M2 macrophages, and activated mast cells, while a decrease was seen in CD8 T cells, resting memory CD4 T cells, and eosinophils." (PMID 40230692, 2025). "We further compared the infiltration differences of each cell type between the sepsis group and the control group using the Wilcoxon test (P < 0.05), and found that there were significant differences in CD4+ memory cells, B cells, CD16+ and CD14+ monocytes, and CD8+ T cells between the two groups." (PMID 41246299, 2025). "Interestingly, we found that age positively correlated with the percent of CD4+ central memory T cells in both sepsis and acute organ dysfunction." (PMID 39935482, 2025). "Notably, IL-10 potently inhibits CD4 Tcell activation and function, whilepromoting proliferation, survival and anti-inflammatory functions of regulatory Tcells in sepsis, which further augment immunosuppression duringsepsis." (PMID 40458301, 2025). "Notably, the functional role of PANoptosis in immune cell populations remains underexplored, particularly regarding the characterization of CD4+ T lymphocytes’ PANoptosis kinetics and regulatory networks during sepsis progression." (PMID 40995563, 2025). "Additionally, TIM-3 knockdown in CD4+ T cells or systemically in sepsis models reduces immunosuppression-related mortality." (PMID 40153575, 2025). "Additionally, ferroptosis has been identified in immune cells, such as CD4+ T cells, macrophages, and dendrite cells during sepsis." (PMID 40715082, 2025). "Thus, elucidating the underlying mechanisms within the inflammatory and anti-inflammatory imbalance in CD4+ T cell subsets during sepsis is of great value." (PMID 40899834, 2025). "Notably, megakaryocyte progenitors and CD4+ memory cells were predominantly found in the sepsis group." (PMID 40124361, 2025). "Its expression is increased in CD4+ T cells of sepsis survivors." (PMID 41158471, 2025). "CM CD4+ T cell proportions were increased in sepsis compared to bacteraemia." (PMID 41208955, 2025). "Notably, NUFIP1-mediated ribophagy of CD4+ T lymphocytes exhibited a significant impact on host immunosuppression status, multiple organ damage, and sepsis prognosis." (PMID 40995563, 2025). "TIM-3: The expression of TIM-3 on CD4+ T cells of sepsis patients increases." (PMID 41209006, 2025). "Simultaneously, PD-1 expression was significantly upregulated, and IL-2 and IFN-γ secretion levels were significantly decreased, suggesting that certain components in sepsis patient serum may promote the functional exhaustion of CD4+ T cells." (PMID 41306770, 2025). "Our data raises the prospect that CD69+ naïve CD4 T cells may be a useful biomarker in the diagnosis of sepsis." (PMID 41208955, 2025).